SMAD3 (SMAD family member 3)
Diseases named in the same sentence as SMAD3 in open-access papers (continued):
Sharing a sentence is not in itself a finding about the gene and the disease.
renal fibrosis (continued). "The findings suggested that TXL ameliorates renal fibrosis by impeding exosomal TGF-β1 transfer from GECs to GMCs by regulating the TGF-β1/Smad3 pathway." (PMID 36105201, 2022). "TGF-β signaling plays a pivotal role in renal fibrosis, and Smad3 is the dominant downstream transcriptional factor controlling the expression of various pro-fibrogenic genes." (PMID 36091385, 2022). "In the UUO and I/R models, SIRT1 activation improved renal fibrosis in proximal tubular cells by deacetylating SMAD3 and SMAD4 and blocking the effect of TGF-β signaling on matrix metalloproteinase-7 (MMP-7), which normally cleaves E-cadherin." (PMID 35277012, 2022). "Our recent studies have shown that blockade of HDAC6 with ACY-1215 also attenuated renal fibrosis through a mechanism involving the inactivation of TGFβ1/Smad3, EGFR/AKT, STAT3 and NF-κB signaling pathways in a murine model of UUO injury." (PMID 35559244, 2022). "In the experimental model of obstructive nephropathy inhibition of mir-29 by TGF-beta/Smad3 was related with enhanced renal fibrosis." (PMID 34312814, 2022). "Our previous studies demonstrated the combined treatment of AA and NG effectively inhibited Smad3-mediated renal fibrosis in the UUO-injured mouse model." (PMID 36147472, 2022). "The acetylation of Smad3 (Ac-Smad3) level was high in the rats with cardiac fibrosis and renal fibrosis, while it was low in the normal myocardium and nephridial tissue of rats." (PMID 35081907, 2022). "Other studies have shown that TGF-β1/Smad3 signaling pathway and miR-21 also play important roles in renal fibrosis and inflammation." (PMID 35744807, 2022). "This indicates that lncRNA can specifically inhibit TGF-β–induced Smad3 phosphorylation and downstream pro-fibrotic gene expression from alleviating renal fibrosis." (PMID 36299256, 2022). "In UUO mice models, Previous studies in our group find that PRMT1 and H4R3me2a are up-regulated in the UUO mice models, and inhibition of PRMT1 via AMI-1 can inhibit the activation of TGF-β/Smad3 signaling pathway and alleviate renal fibrosis." (PMID 35559246, 2022). "Glycogen synthase kinase 3β (GSK3β) is a serine/threonine-protein kinase that inhibits the CREB activities while promoting CBP binding to Smad3 to facilitate renal fibrosis." (PMID 35541902, 2022). "Those processes in Smad3 mediating renal fibrosis were via miR-29 and miR-200 downregulation and miR-21, miR-129, and miR-210 upregulation." (PMID 35990655, 2022). "Taken together, these findings clearly demonstrated that AANG preventive treatment effectively inhibits Smad3-mediated renal fibrosis and NF-κB -driven renal inflammation, thereby protecting the kidney from the development of T2DN in db/db mice." (PMID 36147472, 2022). "After the binding of Smad3 and Smad4, they enter the nucleus and directly mediate renal fibrosis by promoting DNA methylation, reducing histone acetylation, and inducing miRNA transcription." (PMID 36105187, 2022). "It has been reported that many microRNAs take part in renal fibrosis and are regulated in a Smad3-dependent manner." (PMID 36091385, 2022). "Overproduction of TGF-β1 and subsequent activation of the TGF-β1/Smad3 pathway is the most important mechanism for various insults to induce renal fibrosis and promote the progression of CKD to ESRD." (PMID 35847036, 2022). "Previous studies revealed that miR-433 plays a regulatory role in tissue fibrosis, it promotes renal fibrosis by targeting AZIN1 to activate the TGF-β/SMAD3 signaling pathway." (PMID 35255830, 2022). "The bone morphogenetic protein-7 (BMP7) is capable of inhibiting TGF-β/Smad3 signaling, which subsequently results in protecting the kidney from renal fibrosis, but its lower blood retention and osteogenic activity are bottlenecks for its clinical application." (PMID 35890230, 2022). "We thus examined the mechanisms of preventive versus intervention therapy with AANG on Smad3-mediated renal fibrosis." (PMID 36147472, 2022).
renal fibrosis (continued). "TGF-β1 has long been known as a key mediator in the pathogenesis of renal fibrosis by activating the downstream Smad proteins, especially Smad3." (PMID 35541902, 2022). "miR-192 is one of the most abundant miRNAs in the kidney and contributes to alleviating renal fibrosis by inhibiting TGF-β/Smad3 signaling." (PMID 36105201, 2022). "Mechanistically, AANG effectively prevented both Smad3-mediated renal fibrosis and NF-κB-driven renal inflammation in the diabetic kidney in vivo and advanced glycation end-products (AGE) stimulated tubular epithelial mTEC cells in vitro." (PMID 36147472, 2022). "TGF-β1/Smad3 signaling has been considered a significant pathway in glomerular mesangial cells (GMCs) activation and renal fibrosis." (PMID 36105201, 2022). "This is also confirmed by deleting Smad3 to inhibit UUO-induced renal fibrosis in CRP transgenic mice." (PMID 35541902, 2022). "Inhibition or knockout of Smad3 reduces renal fibrosis in diabetic nephropathy and ureteral obstruction nephropathy." (PMID 35439976, 2022). "Long noncoding RNA (lnc-TSI) blocked the interaction of Smad3 with TGFBR1 by binding with the MH2 domain of Smad3 and attenuated renal fibrosis." (PMID 35680856, 2022). "Mechanistically, TGF-β1/Smad3 signaling activations are crucial players in renal fibrosis and inflammation of diabetic nephropathy." (PMID 34775979, 2021). "We also investigated the functional role of Smad3 in CRP-induced renal fibrosis using Smad3 stable knockdown NRK52E TECs." (PMID 34671208, 2021). "Encouragingly, it has been reported that a group of characterized lncRNAs is involved in TGF-β/Smad3-mediated renal fibrosis and inflammation." (PMID 34054586, 2021). "The central role for Smad7 in CRS was demonstrated in a Smad7 deficiency model, which resulted in enhanced ANG II‐induced loss of miR‐29b expression and the promotion of murine cardiac and renal fibrosis through activation of TGF‐β/Smad3 and NF‐kB signaling." (PMID 33529442, 2021). "Results from this study provided evidence for an essential role of Smad3 signalling in the pathogenesis of UUO-induced renal fibrosis and inflammation under high CRP conditions." (PMID 34671208, 2021). "Our recent study demonstrated that HDAC6 contribute to fibrosis by direct activation of renal interstitial fibroblast, HDAC6 involve in renal fibrosis by the activation of TGF-β1/Smad3 and EGFR signaling pathways in UUO model." (PMID 33896334, 2021). "Another study then revealed that resveratrol, an activator of Sirt1, attenuated the progress of renal fibrosis both in vitro and in vivo by inhibiting the TGF-β/SMAD3 signaling pathway and reducing the stress caused by reactive oxygen species." (PMID 33906673, 2021). "Smad3 directly binds to the promoter region of collagens to trigger renal fibrosis production and reduces the activity of MMP-1 to inhibit ECM degradation via induction of TIMP-1." (PMID 34299192, 2021). "The regulatory role of SIRT1 to TGF‐β signaling has also been revealed recently, and it is reported that SIRT1 inhibits the TGF‐β/Smad3 pathway to attenuate renal fibrosis." (PMID 33906673, 2021). "The protection against TGF-β1/Smad3-mediated renal fibrosis and NF-κB-driven renal inflammation are likely mechanisms by which deletion of Smad3 ameliorated kidney injury in CRP Tg mice with UUO." (PMID 34671208, 2021). "An increasing number of studies illustrate that TGF-β1/Smad3 signalling is critical in the progression of renal fibrosis and resultant CKD." (PMID 34671208, 2021). "Overall, our results suggest that miR299a-5p inhibition in vivo ameliorates renal fibrosis and protects against the progression of CKD, associated with inhibition of Smad3 activation." (PMID 33420269, 2021). "SIS3 treatment reduced the phosphorylation of Smad3 and ameliorated renal fibrosis by downregulating the expression of fibronectin and collagen I." (PMID 34938805, 2021).
renal fibrosis (continued). "By contrast, the function of Smad2 and Smad7 is protective, which negatively regulates the TGF-β/Smad3 signaling in renal fibrosis and inflammation." (PMID 34054586, 2021). "The key finding of this study is that renal fibrosis and the suppression of fatty acid oxidation occurred in HN rats and were associated with activation of the TGF-β1/Smad3 signaling pathway." (PMID 34938805, 2021). "We reported CRP can activate NF-κB-mediated renal inflammation and TGF-β/Smad3-mediated renal fibrosis via CD32b in diabetic kidney disease." (PMID 34671208, 2021). "HIPK2, a regulator of the TGF-β1/Smad3 pathway, inhibited Smad3 phosphorylation, leading to the mitigation of renal fibrosis, which indicated that Smad3 is a potential therapeutic target for T2DN." (PMID 34327204, 2021). "Smad4, the same as Smad3, promotes fibrogenesis, which was proven by the observation of reduced collagen I expression and inhibited renal fibrosis in the Smad4 knock-out mouse model." (PMID 34327204, 2021). "By using RNA sequencing, many Smad3-dependent lncRNAs have been identified and found to play critical roles in renal fibrosis and inflammation." (PMID 34360646, 2021). "In the canonical pathway, Smad2 and Smad3 are two key downstream mediators of TGF-β receptor that are highly activated in renal fibrosis." (PMID 33718407, 2021). "lnc-TSI inhibits renal fibrosis by binding to the MH2 domain of Smad3, therefore blocking the interaction of Smad3 and TβRI and inhibiting the phosphorylation of Smad3." (PMID 34054586, 2021). "We also explored the mechanisms by which Smad3 KO mice were protected against CRP-induced renal fibrosis in vivo and in vitro." (PMID 34671208, 2021). "TGF-β1/Smad3 signalling has been suggested as the main molecular mechanism in renal fibrosis due to several studies with various models." (PMID 34003249, 2021). "In contrast to the first phase, the second or myogenic phase is inhibited by Smad3, a finding consistent with reports showing that Smad3 levels decrease with the progression of (renal) fibrosis." (PMID 34204945, 2021). "Erbb4-IR correlates negatively with SMAD7 expression and either inhibits or promotes TGF-β/Smad3-mediated renal fibrosis in vivo and in vitro." (PMID 34059951, 2021). "Phosphorylation of Smad3 that was enhanced in cell and animal models for renal fibrosis was attenuated by remdesivir." (PMID 34276356, 2021). "Of note, many TGF-β/Smad3-regulated lncRNAs have been reported as essential mediators in the process of renal fibrosis and inflammation." (PMID 34054586, 2021). "Proto-oncogene tyrosine protein kinase Src and neural transcription factor Pou4f1 have been identified as key downstream regulators in the TGF-β1/Smad3 signaling for promoting renal fibrosis via macrophage-myofibroblast transition (MMT)." (PMID 34299192, 2021). "Loss of intrarenal miR-29b is able to inhibiting the progression of DKD via TGF-β/Smad3-dependent renal fibrosis and NF-κB-driven renal inflammation." (PMID 33883002, 2021). "TGF-β1/Smad3 signaling pathway mediated renal fibrosis and NF-κB-driven renal inflammation are important pathological procedures to impair renal function in diabetic nephropathy." (PMID 34775979, 2021). "As the most potent fibrogenic factor, TGF-β was considered to contribute to HUA-mediated renal fibrosis via the activation of Smad3." (PMID 35153751, 2021). "Next, we examined the effect of Smad3 deletion on CRP-induced renal fibrosis and inflammation in UUO mice." (PMID 34671208, 2021). "The use of either a Smad3-specific inhibitor or Smad3 gene knockdown consistently confirmed a delayed transdifferentiation of proximal tubular cells and reduced renal fibrosis in diabetic mice." (PMID 33670735, 2021). "In conclusion, we showed that RDV inhibits renal fibrosis in obstructed kidneys, which is correlated with reduced phosphorylation of Smad3 and increased expression of Smad7." (PMID 34276356, 2021).
renal fibrosis (continued). "In view of DN, mice null for Smad3 are protected from renal fibrosis including GBM thickening and ECM overproduction in STZ-induced DN, although inhibition of albuminuria is always observed." (PMID 34360646, 2021). "It plays an important role in mediating renal fibrosis by enhancing Smad7 degradation, Smad3 phosphorylation, and TGF-β receptor 1 expression." (PMID 34059951, 2021). "Smad signaling is the major pathway of TGF-β1 signaling in renal fibrosis, and Smad3 has been shown to mediate renal fibrosis in various mouse models of chronic kidney diseases." (PMID 33614642, 2021). "One of the major molecular pathways driving renal fibrosis is believed to be the canonical TGF-β1/Smad3 pathway." (PMID 34003249, 2021). "The TGF‐β1/Smad3 pathway was reported to be a pivotal pathway for the progression of renal fibrosis." (PMID 32969198, 2020). "Few recent studies have reported that Smad3 silencing reduces the severity of renal fibrosis and that Smad2 promotes EMT by up-regulating CTGF and VEGF expressions in mice." (PMID 32515466, 2020). "We previously showed that the allosteric inhibition of HIPK2 and Smad3 interaction by small-molecule inhibitor BT173 effectively reduces the renal fibrosis in UUO and Tg26 mouse models." (PMID 32701510, 2020). "It is now well accepted that Smad3 is a key profibrotic transcription factor and plays an essential role in cardiovascular and renal fibrosis under high Ang II conditions." (PMID 32971570, 2020). "Deleting Smad4 from renal tubular cells alleviates renal fibrosis in a mouse model of UUO by suppressing Smad3 function." (PMID 32613000, 2020). "For instance, studies have demonstrated that TGF-β/Smad3 promotes renal fibrosis by inducing the expression of miR-21, miR-433, and miR-192, which in turn suppressed PTEN, Smad7, ZEB1/2, and AZIN1, respectively." (PMID 32587662, 2020). "In the murine intra-arterial CI-AKI model, there was increased hypoxia and TGF-β1/SMAD3 pathway activation and collagen expression, resulting in renal fibrosis." (PMID 32200666, 2020). "Overexpression of Smad2 attenuated TGF-β1-induced phosphorylated Smad3 and collagen expression, whereas deletion of Smad2 promoted renal fibrosis via substantially enhanced Smad3 signaling." (PMID 32266267, 2020). "Erbb4-IR is a novel lncRNA responsible for TGF-β1/Smad3-mediated renal fibrosis and it is a specific therapeutic target for chronic kidney disease (CKD)." (PMID 32295041, 2020). "Consistently, conditional deletion of TβRII from mice results in protection against TGF-β/Smad3-mediated renal fibrosis while enhancing NF-κB-driven renal inflammation." (PMID 32258028, 2020). "Either a Smad3 knockout or a Smad3-specific inhibitor delayed de-differentiation of proximal tubular cells and alleviated renal fibrosis in a streptozotocin-induced model of diabetes." (PMID 32266267, 2020). "Present results, therefore, support the notion that TGF‐β/Smad‐related proteins p‐Smad2 as well as p‐Smad3 are up‐regulated, whereas Smad7 expression decreased in renal fibrosis models compared with that in the controls." (PMID 32253812, 2020). "This notion was supported by evidence that EndoMT in streptozotocin-induced diabetic nephropathy associates with Smad3, which participates in the TGF-β1 pathway and plays an essential role in renal fibrosis." (PMID 32268503, 2020). "Silencing Erbb4-IR was shown in vitro to block TGF-β1-induced collagen I and α-SMA expressions, and effectively attenuate renal fibrosis by inhibiting TGF-β1/Smad3 signaling." (PMID 32295041, 2020). "In contrast, Erbb4-IR is another novel Smad3-dependent lncRNA capable of inhibiting renal fibrosis by targeting miR-29b and Smad7 in both obstructive nephropathy and type II diabetic nephropathy, respectively." (PMID 32258028, 2020).
renal fibrosis (continued). "This study also identified Erbb4-IR as responsible for TGF-β/Smad3-mediated renal fibrosis by downregulating Smad7." (PMID 32295041, 2020). "We also find that Ang II can induce an E3‐ligase, Smurf2, which can bind and degrade Smad7, thereby promoting Smad3‐dependent renal fibrosis and NF‐κB‐mediated renal inflammation." (PMID 32971570, 2020). "Knock-down of Smad3 in mice significantly attenuated renal fibrosis in diabetic nephropathy and aristolochic acid-induced nephropathy." (PMID 32957963, 2020). "NLRP3 also has inflammasome-independent effects in tubular epithelial cells, including participating in SMAD2 and SMAD3 phosphorylation in response to TGFβ signaling, triggering renal fibrosis." (PMID 32521623, 2020). "It is also reported that the formation of Smad3/Smad4/CDK9 complex drives renal fibrosis during ureteral obstruction." (PMID 32258028, 2020). "More specifically, miR-192 is a critical downstream mediator of TGFβ/Smad3 signaling in the development of renal fibrosis." (PMID 32024063, 2020). "No additive effects were observed in Pax8-HIPK2KD mice treated with BT173, indicating that both kinase activity of HIPK2 and interaction of HIPK2 with Smad3 are both required for HIPK2 to promote renal fibrosis." (PMID 32701510, 2020). "In summary, these data collectively suggest inhibitors of HIPK2, either inhibiting the kinase activity or its interaction with downstream effectors such as Smad3, would be therapeutically effective against renal fibrosis in CKD." (PMID 32701510, 2020). "Mechanistically, deletion of Smad4 inhibits renal fibrosis by suppressing Smad3 promoter activity and blocking the binding of Smad3 to the collagen promoter without affecting its phosphorylation and nuclear translocation." (PMID 32258028, 2020). "In published experimental studies, it has been demonstrated that the suppression of the TGF-β1/Smad3 pathway significantly attenuates renal fibrosis by the ablation of profibrotic regulators." (PMID 31220088, 2019). "Many studies have shown that targeting Smad3 can improve the development and progression of tissue fibrosis in vivo, including experimental models of renal fibrosis, pulmonary fibrosis, and liver fibrosis." (PMID 31652997, 2019). "On the other hand, Smad7 suppresses renal fibrosis by altering the expression of TGF-β/Smad3 through microRNAs." (PMID 31531112, 2019). "In the TGF-β/Smad pathway, Smad2 and Smad3 were known to accelerate renal fibrosis, whereas Smad 7 can inhibit TGF-β signal transduction to prevent fibrosis." (PMID 31687039, 2019). "Although Smad2 and Smad3 have more than 90% homology in amino acid sequence and interact physically, their functions differ in renal fibrosis." (PMID 31754396, 2019). "This was associated with SIRT1 upregulation and reduced phosphorylated Smad3, indicating partial reduction of renal fibrosis by low (25 mg/kg/day) RSV treatment." (PMID 31319485, 2019). "Excessive activation of NLRP3 inflammasome and down-regulation of Sirt1/Smad3 deacetylation pathway play a significant role in the evolution of renal fibrosis." (PMID 31118021, 2019). "Smad3 promotes renal fibrosis by directly binding to the promoter region of ECM components to trigger their production." (PMID 31557800, 2019). "TGF-βR2 signaling via TGF-β/Smad3 or NF-κB in kidney fibroblasts or tubular epithelial cells exerts diverse effects during renal fibrosis and inflammation." (PMID 31597574, 2019). "Transforming growth factor‐β1 (TGF‐β1)/Smad3‐driven renal fibrosis is the common pathogenesis of obstructive nephropathy." (PMID 31211499, 2019). "Another example is ErbB4-immunoreactivity (Erbb4-IR), which is a novel lncRNA that contributes to TGF-β/Smad3-mediated renal fibrosis and a potential therapeutic target for chronic fibrotic kidney disease." (PMID 31281667, 2019).